HMOX1 (heme oxygenase 1)
Diseases named in the same sentence as HMOX1 in open-access papers (continued):
Sharing a sentence is not in itself a finding about the gene and the disease.
colitis (146 papers, 2010 to 2026). Inflammation of the colon. "Induction of heme oxygenase-1 (HO-1/Hmox1) is broadly considered cytoprotective, but the role of colonic epithelial HO-1 in colitis-associated tumorigenesis is poorly defined." (PMID 41410530, 2025). "It was also recently described an essential role of CX3CR1+ gut macrophages in resolving inflammation in the intestine, where they protect against colitis-associated cancer by regulating HMOX-1 expression." (PMID 39611159, 2024). "Among them, heme oxygenase-1 (HO-1) presents pronounced anti-inflammatory and antioxidative properties in protecting mice from colitis-associated inflammatory injury and oxidative stress." (PMID 34733403, 2021). "In support of this observation, another study showed that mice treated with the HMOX1 inducer hemin previous to the induction of DSS colitis displayed reduced histological damage, which was associated to an increased expression of HMOX1." (PMID 30258436, 2018). "TL has been used to treat experimental colitis in rats, showing a protective anti-inflammatory effect, possibly due to the induction of the anti-inflammatory enzyme heme oxygenase-1 (HO-1)." (PMID 39858939, 2025). "In contrast, the antioxidant enzyme heme oxygenase-1 (HO-1), which attenuates colitis, was elevated." (PMID 38104122, 2023). "Heme oxygenase 1 (HO-1) is significantly upregulated in a DSS-induced model of experimental colitis, exerting anti-inflammatory and antioxidant properties." (PMID 37238692, 2023). "Similar to CUR, APS also protects intestinal epithelial cells (IECs) against ferroptosis by inhibiting Nrf2/HO-1(Heme oxygenase 1) signaling pathways and reduces lesions in a murine model of experimental colitis." (PMID 36193068, 2022). "Analysis of NRF2 target genes involved in ROS detoxification (Nqo1, Gsta2) and heme/iron metabolism (Hmox1) at the apex of acute murine colitis shows a more nuanced picture with all three genes being differentially affected by Nox4 deficiency." (PMID 33059312, 2020). "Another study also described the cytoprotective role of HMOX1 in the model of colitis induced by DSS in mice." (PMID 30258436, 2018). "It has been reported that in the model of colitis induction by the administration of Dextran Sulfate Sodium (DSS) an increase in the expression of HMOX1 led to an amelioration of the intestinal inflammation." (PMID 30258436, 2018). "The simultaneous intrarectal administration of DSS and Tranilast to C57BL/6 mice resulted in an attenuated colitis, produced by low pro-inflammatory cytokines, increased anti-inflammatory cytokines and promoted HMOX1 expression." (PMID 30258436, 2018). "Our findings indicated that Res attenuated dextran sulfate sodium‐induced intestinal epithelial cells barrier dysfunction via activating nuclear factor erythroid‐2‐related factor 2/heme oxygenase 1 (Nrf2/HO‐1)pathway and had great therapeutic potential throughout the preliminary stages of colitis." (PMID 38372468, 2024). "Additionally, saikosaponins alleviate DSS-induced colitis by regulating the NRF2/heme oxygenase-1 pathway." (PMID 38672468, 2024). "Also, L. lactis was successful in transferring IL-17A in cancer mouse model, Heme oxygenase-1 in mice with colitis, and hTFF1 in hamster with oral mucositis." (PMID 38495751, 2024). "Recent studies have suggested that induction of Hmox1 expression in Mø in response to heme may serve a protective function by mitigating colonic inflammation and damage in animal models of colitis." (PMID 37342339, 2023). "In addition, a recent study also demonstrated that dandelion root extract exerted protective effects on DSS‐induced colitis by repressing NF‐κB and inducing heme oxygenase‐1 (HO‐1)." (PMID 37970386, 2023). "Moreover, agents that enhance heme oxygenase-1 activity and increase Nrf2 levels in experimentally induced colitis were reported to reduce ROS production, possibly via suppression of NF-κB activity and inhibition of iNOS expression in the colonic tissues." (PMID 35631426, 2022).
colitis (continued). "In the case of colitis, one study demonstrated that inflammasome activation could be inhibited via activation of Nrf2 and its downstream response protein heme oxygenase-1 (HO-1), responsible for intracellular antioxidant defenses." (PMID 32751530, 2020). "Moreover, nanoparticles derived from grapefruit are taken up by intestinal macrophages and improve experimental colitis in mice by upregulating the expression of heme oxygenase-1 (HO-1) and inhibiting the production of IL-1β and TNF-α." (PMID 32365813, 2020). "In vivo evidences showed that dietary QUE could ameliorate experimental colitis in part by modulating the anti-inflammatory effects and bactericidal capacity of macrophages through a heme oxygenase-1 (HO-1)-dependent pathway." (PMID 32599861, 2020). "Therefore, tissue superoxide dismutase (SOD) and catalase enzyme activity was determined in NED-treated DSS colitis animals along with expression of Heme Oxygenase-1 (HO-1) and SOD3 mRNA." (PMID 32650602, 2020). "In addition, grapefruit-derived nanoparticles (GDNs), which are selectively absorbed by intestinal macrophages, can ameliorate dextran sulfate sodium (DSS)-induced colitis by up-regulating heme oxygenase-1 (HO-1) expression and inhibiting the production of inflammatory factors." (PMID 38540732, 2024). "More recently, oral administration of NCT protected against experimental mouse colitis and was accompanied with upregulation of nuclear factor erythroid 2-related factor 2 (Nrf2)-dependent cytoprotective and anti-inflammatory gene expression such as heme oxygenase-1." (PMID 35628790, 2022). "GRP supplementation activated Nrf2, increased the levels of heme oxygenase-1 (HO-1) and xanthine oxidase and reduced the 8-hydroxydeoxyguanosine levels in DSS-induced colitis mice." (PMID 39517291, 2024). "Nevertheless, BM-MSC treatments downregulated Nos2, Arg1, Gata3, Mrc1 and Hmox1 which were upregulated in Winnie mice and IBD patients; but are reportedly also upregulated by MSCs in chemical models of colitis." (PMID 38503815, 2024). "Genes representative of anti-inflammatory macrophage polarization (Mrc1, Hmox1, Arg1 and Chi3l3) were either unchanged or downregulated by MSC treatments in contrast to some reports in acute chemically-induced colitis models." (PMID 38503815, 2024). "In the model of colitis induction by administration of Dextran Sulfate Sodium (DSS), administration of HMOX1 inductor/activator CoPP significantly reduced the intestinal histological damage as compared to control animals." (PMID 39611159, 2024). "Similarly, a study reported that quercetin could ameliorate DSS-induced colitis in a mouse model by remodeling macrophages’ proinflammatory activity via a heme oxygenase-1 (HO-1)-dependent pathway and maintaining gut microbial diversity and commensal microbe homeostasis." (PMID 37107341, 2023). "Additionally, treatment with 25 and 50 mg/kg of syringic acid increased the mRNA expression of heme oxygenase-1 (Ho-1), NAD(P)H: quinone acceptor oxidoreductase 1 (NQO1), and NRF2 in colon tissue in acetic acid-induced colitis rats." (PMID 38732594, 2024). "We also detected oxidative stress-related biomarkers, inflammatory cytokines, and potential nuclear factor erythroid 2-related factor 2 (Nrf2)/heme oxygenase 1 (HO-1) and janus kinase 2 (JAK2)/signal transducer and activator of transcription 3 (STAT3) pathways in the colitis tissues." (PMID 39133435, 2024). "Colitis attenuation is attained by co-modulating MAPK and Nrf2/Hmox-1 signaling pathways." (PMID 37359553, 2023). "By regulating the anti-inflammatory effects and bactericidal activity of macrophages through heme oxygenase-1 (HO-1)-dependent pathway, QCT may reduce the severity of experimental colitis." (PMID 37701897, 2023).
colitis (continued). "On the other side, DSS-induced colitis in COX-2−/− KO mice was less severe compared to WT control mice, showing a decrease of heme oxygenase-1 (HO-1) and increase of NADPH quinone oxidoreductase-1 (NQO-1), demonstrating the tight association between inflammation and the antioxidant system." (PMID 31434263, 2019). "In studies involving murine colitis models, the activation of Nrf2 improved epithelial integrity and reduced IBD severity by upregulating antioxidant enzymes such as NAD(P)H quinone oxidoreductase 1 (NQO1), heme oxygenase-1 (HO-1), and glutathione S-transferase (GST)." (PMID 40563329, 2025). "While heme has been widely used to induce Hmox1 expression, no data are available on the protective role of HO-1 in the intestinal barrier disruption after doxorubicin treatment, mimicking the physiological process of colitis." (PMID 37342339, 2023). "Moreover, the upregulation of anti-oxidative genes, including ferritin heavy chain 1, heme oxygenase 1, NAD(P)H quinone oxidoreductase 1, and superoxide dismutase 1, in the colons of colitis/SPH group was observed compared with the control peptide treatment group." (PMID 36139127, 2022).
Obesity (143 papers, 2010 to 2026). Accumulation of substantial excess body fat. "This study shows that the rs7211 polymorphism in the TXNIP gene and the rs2071749 of the HMOX1 gene are associated with obesity in Mexican mestizo people." (PMID 27274779, 2016). "The rs2071749 polymorphism in the HMOX1 gene was significantly associated with obesity when it was analyzed under a dominant model." (PMID 27274779, 2016). "Previous studies have demonstrated that induction of heme oxygenase-1 results in weight loss in several rodent models of obesity." (PMID 26217498, 2014). "We found that the HMOX1 rs2071746T/A and (GT)n repeat polymorphisms may contribute to obesity, oxidative stress, endocrine abnormalities, and metabolic disorders." (PMID 41262262, 2025). "This study investigated the impact of ALDH2 deficiency on diet-induced obesity and AF vulnerability in mice, exploring potential compensatory upregulation of nuclear factor erythroid 2-related factor 2 (Nrf2) and heme-oxygenase 1 (HO-1)." (PMID 38396862, 2024). "HMOX1 is a metabolic enzyme critically important for heme degradation that is implicated in excess intracellular iron storage and adipose tissue inflammation in obesity, but also in adipose tissue browning." (PMID 37931470, 2023). "The RAPA‐ and RAPA/MET‐induced reduction in adipose tissue myeloid infiltration and expression of genes for inflammatory stress‐responsive factors and cell senescence (Itgam, Itgax, Hmox1, Lbp, and Serpine1) demonstrate that these treatments specifically suppress obesity‐associated inflammation." (PMID 35986566, 2022). "However, further studies to clarify the relationship between HMOX1 polymorphisms and obesity in different populations are warranted, because the mean BMI of subjects was relatively low (27.81 ± 2.39) in the obese group of this study." (PMID 30024897, 2018). "Recent research has highlighted the role of heme oxygenase-1 (HO-1) in the modulation of obesity-related pathways." (PMID 39195446, 2024). "In the case of anti-obesity, quercetin is reported to have the ability to stimulate hepatic mitochondrial oxidative metabolism through the induction of heme oxygenase-1 (HO-1) in the nuclear factor-related erythroid factor 2, Nrf-2 pathway." (PMID 39713250, 2024). "HMOX1 is an important factor of obesity, tissue dysfunction, intestinal inflammation and metabolic disturbances." (PMID 36593446, 2023). "Quercetin also improves mitochondrial respiration and prevents obesity-induced hepatic lipid degeneration by boosting heme oxygenase 1(HO-1) via the Nrf2 pathway." (PMID 37570615, 2023). "Because we have previously shown that pregnant mice with a partial deficiency of Hmox1 have placentas with vascular defects and also have increased weight gain and visceral fat, we speculate that there is an association between obesity, placental vascular defects, and Hmox1 expression." (PMID 37948457, 2023). "In a genetic model of obesity, EtOH upregulated oxidative stress markers, such as heme oxygenase 1 (Hmox1), while EtOH has also been found to downregulate oxidative stress in HFD-fed mice." (PMID 37134024, 2023). "The nuclear factor erythroid 2-related factor 2/heme oxygenase-1 (Nrf2/HO-1) signaling pathway is closely related to pancreatic β-cell injury, obesity, glucose metabolism disorders, and insulin resistance." (PMID 35211009, 2022). "The induction of HMOX-1 has been suggested as the mechanism by which CoPP displays its anti-obesity activity." (PMID 34071361, 2021). "Increasing heme oxygenase-1 (HO-1) activity can reverse complications related to obesity, metabolic syndrome, and MAFLD." (PMID 33363067, 2020). "The study aim was to demonstrate that adipocyte-specific HO-1 (heme oxygenase-1) gene therapy is a therapeutic approach for preventing the development of obesity-induced metabolic disease in an obese-mice model." (PMID 31906399, 2020).
Obesity (continued). "Induction of heme oxygenase-1 (HO-1) has been demonstrated to decrease body weight and improve insulin sensitivity in several models of obesity in rodents." (PMID 28287466, 2017). "Investigations are therefore underway to identify predictors or biomarkers of healthy versus unhealthy obesity, such as heme oxygenase-1, to allow clinicians to better personalize treatment." (PMID 25361574, 2014). "Controversially, the conditional deletion of HMOX-1 in murine macrophages protected mice from obesity-induced inflammation and insulin resistance suggesting an atheroprotective role of HMOX-1." (PMID 25152735, 2014). "Furthermore, elevated HMOX1 levels were related to a slight but significant increase in the risk of PCOS, and the rs2071746T/A and (GT)n genetic variants significantly affected obesity, oxidative stress, endocrine abnormalities, and metabolic disorders." (PMID 41262262, 2025). "We assessed body weight of Hmox1-/- and Hmox2-/- mice as well as their WT littermates at 4–5 months of age to determine whether the mice had early evidence of obesity." (PMID 32992485, 2020). "Because MnTBAP is a metalloporphyrin molecule, we hypothesized that its anti-obesity and insulin sensitizing actions may be regulated by heme oxygenase-1 (HO-1), as had been shown for cobalt porphyrins." (PMID 26397111, 2015). "Additionally, its inhibitory effect on obesity-induced inflammation operates through the activation of the nuclear factor erythroid 2-related factor–heme oxygenase-1 (Nrf2-HO-1) signaling pathway, suggesting its crucial role in the anti-inflammatory effects of brassinin." (PMID 38792249, 2024). "Notably, Pcsk1 and Hmox1 play important roles in preventing obesity and metabolic disease." (PMID 37770553, 2023). "In addition to adipokines, increased expression of genes such as Pcsk1 and Hmox1, which play important roles in preventing obesity and metabolic disease, could potentially contribute to reducing the risk of metabolic disease post slurry treatment." (PMID 37770553, 2023). "Together these findings demonstrate that endothelial activation of HMOX1 could play an important role in the treatment/prevention of obesity, and further highlight the importance of AMPK-dependent signaling in mediating the anti-obesogenic effects of bilirubin." (PMID 32082188, 2020). "Therefore, promoter methylation was investigated at these loci, as well as at previously identified gene promoters reported in the literature to be regulated by DNA methylation in response to high-fat diet, obesity or T2D (Leptin, Pparg, Glut4, Fasn, Irs1, Hmox1, Fabp4)." (PMID 30728429, 2019). "Other nominally significant associations were established between WHOCS scales and: IFNL4 rs12979860, ACEIs, obesity, ARA-II, HCP5 rs2395029, ACE rs1799752, DPP4 rs17574, HMOX1 rs2071746, IL10 rs1800896, IL6 rs1818879, NFKB1 rs28362491, and MX1 rs469390." (PMID 35636966, 2022). "Obesity and ROS induction contribute to an increase in NOV and reduction in heme oxygenase-1 (HO-1) levels." (PMID 33918360, 2021). "In the study, poly(lactic-co-glycolic acid) (PLGA) NPs were loaded with heme oxygenase-1 (HO-1) inducers (iron protoporphyrin ix (hemin) or cobalt protoporphyrin ix (CoPP)) and surface modified with AHP then used for the treatment of obesity-induced T2DM and diet-induced MASH in mice models." (PMID 40560451, 2025). "Obesity is characterized by permanently increased oxidative stress and Akt kinase as a part of Akt/Nrf2/ARE signaling plays an important role in increasing the activity of antioxidative enzymes such as SOD and heme oxygenase-1 (HO-1)." (PMID 33923282, 2021).